MUC5AC (mucin 5AC, oligomeric mucus/gel-forming)
Diseases named in the same sentence as MUC5AC in open-access papers (continued):
Sharing a sentence is not in itself a finding about the gene and the disease.
intraductal papillary mucinous neoplasms (13 papers, 2011 to 2023). "The alpha-linked glycoform of MUC5AC was unique to intraductal papillary mucinous neoplasms (IPMN), whereas terminal beta-linked GlcNAc was increased in both IPMNs and mucinous cystic neoplasms (MCN)." (PMID 27992432, 2016). "MUC5AC is also expressed in other types of pancreatic lesions such as the intestinal type of intraductal papillary mucinous neoplasm (IPMN)." (PMID 33182511, 2020). "Moreover, MUC5AC levels in subjects with certain pancreatic cysts that have malignant potential, e.g., mucinous cystic neoplasm and intraductal papillary mucinous neoplasm, require further investigation." (PMID 32028958, 2020). "We selected MUC1, MUC2, and MUC5AC for further investigation because they were routinely stained in the postoperative pathological reports of FUSCC for antidiastole and grading of intraductal papillary mucinous neoplasms." (PMID 35910854, 2022). "The hyperplastic epithelium of these lesions is variably positive for gastric-type mucins, such as MUC5AC and MUC6, resembling pancreatic intraductal papillary mucinous neoplasm of the branch duct type, and the degree of atypia ranges from low- to high-grade." (PMID 33317146, 2020). "It was shown that the intestinal subtype of IPNB was more frequently positive for MUC1 and less frequently positive for MUC2, MUC5AC and CDX2 (a MUC2 regulating transcription factor), compared to each subtype of pancreatic IPMN." (PMID 30875782, 2019). "This does not explain what triggers MUC5AC expression and why it does not transform all pancreatic cells into cancerous ones (MUC5AC is detected in some benign diseases, such as intraductal papillary mucinous neoplasms or IPMN)." (PMID 37175794, 2023).
Allergy (12 papers, 2009 to 2025). An allergy is an immune response or reaction to substances that are usually not harmful. "MUC5B is the primary mucin responsible for routine mucociliary clearance, whereas MUC5AC is induced during infection and uniquely underlies airway hyperreactivity in allergy." (PMID 40035770, 2025). "Potentially more downstream of the effects of C3 and chemokines are the other strongly DE genes that were upregulated in S + C swine and associated with allergy—the mucin MUC5AC, and the serum amyloid A 3 (SAA3)." (PMID 36452260, 2022). "Expressions of mucin genes implicated in allergy, Muc5ac and Muc5b, were elevated and followed a similar trend to GC numbers." (PMID 29511677, 2018). "Similar to cigarette smoke, after a 3-day exposure to e-cigarette aerosols, there were higher levels of Muc5ac, a predominant gel-forming mucin that is induced during allergy, and it also increased in the airways of smokers and e-cigarette users." (PMID 32429092, 2020). "For example, increased miR-145-5p downregulates Muc5ac expression in an OVA-induced model of allergy." (PMID 32477356, 2020). "The gel-forming mucin, Muc5ac, is overproduced and secreted by airway epithelial cells in human allergy and allergic mouse models." (PMID 30845921, 2019). "Increased levels of IL-13, according to the Th2 response after traffic-related PM2.5 exposure, might stimulate goblet cell differentiation and MUC5AC production at the conjunctivae, which is a common pathogenesis in allergic diseases." (PMID 32344779, 2020). "An increased expression of Muc5AC mRNA was also noted in murine and human allergic diseases." (PMID 19158956, 2009). "Studies have shown that Th2-related cytokines such as IL-4, IL-5, and IL-13 can participate in the expression and secretion of mucin genes MUC5AC and MUC5B,29, 30, 31 further indicating the role of allergy in the occurrence and development of ETD." (PMID 38274710, 2024).
chronic rhinosinusitis (12 papers, 2014 to 2025). Chronic form of sinusitis. "The two most prevalent diseases of the nasal mucosa are allergic rhinitis (AR) and chronic rhinosinusitis, both of which share common characteristics, including increased mucin 5AC (MUC5AC) and MUC5B secretion." (PMID 39958344, 2025). "Next, we sought to determine the expression levels of the MUC5AC and MUC5B genes in all patient samples because the respective mucins secreted by nasal epithelial cells have been implicated in chronic rhinosinusitis pathology." (PMID 36902594, 2023). "This study was conducted to determine the roles and mechanisms of IL-19, a member of the IL-20 subfamily, in regulating MUC5AC production in chronic rhinosinusitis (CRS)." (PMID 31379870, 2019). "Our results also further validate our proposal that IL-19 up-regulates MUC5AC production in chronic rhinosinusitis via the STAT3 pathway." (PMID 31379870, 2019). "MUC2 and MUC5AC expressed in chronic sinusitis mucus behave differently on reduction and proteolytic digestion." (PMID 25691903, 2015). "Among them, MUC5AC and MUC5B, two major secretory mucins found in the airway, are over-produced in chronic rhinosinusitis." (PMID 24840724, 2014). "In conclusion, as part of this study we performed bacterial biofilm status evaluation and MUC5AC and MUC5B gene expression quantification in both control and chronic rhinosinusitis patient samples in order to shed light on the possible link between these factors and CRS pathogenesis." (PMID 36902594, 2023). "An anoxic condition is physiologically not relevant to chronic sinusitis, but the sinus mucosa chronically exposed to hypoxic condition may have an influence on MUC5AC secretion." (PMID 24840724, 2014).
colitis (12 papers, 2018 to 2025). Inflammation of the colon. "During DSS colitis, Muc2 and Muc3 expression was selectively reduced in Nr2f6-deficient colonic scrapings whereas Muc1, Muc4 and Muc5ac expression was unaltered." (PMID 28779026, 2018). "In Muc5ac−/− mice with DSS colitis, there is an increase in bacterial-epithelial contact and neutrophil recruitment to the colon, therefore, the loss of Muc5ac may exacerbate injury and inflammation in experimental murine colitis." (PMID 34638564, 2021). "For instance, MUC5AC−/− mice exhibit exacerbated tissue damage, heightened inflammation, and increased bacterial penetration through the mucus layer in DSS colitis, underscoring MUC5AC’s protective role." (PMID 40177488, 2025). "Using knockout mouse models with chemically induced colitis, MUC5AC expression has been shown to protect the intestinal barrier through preventing bacterial translocation across the mucosal layer." (PMID 38612988, 2024). "A reduced expression of muc2 has also been reported in colitis mice, while in contrast, an increased expression of muc5ac was observed in murine colitis." (PMID 35911682, 2022). "Here, we show that MUC5ac was reduced following the induction of chemical colitis, probably because of mucosal cell destruction and of the detergent effect of DSS on the mucus layer." (PMID 33927713, 2021). "MUC5AC is usually expressed in the stomach, trachea, and bronchus, and is typically absent in the healthy colon, but is markedly upregulated in ulcerative colitis (UC) and experimental colitis." (PMID 40177488, 2025). "According to our data, DSS treatment significantly reduced the expression of MUC2 and MUC5AC, whereas APS-H alleviated DSS-induced colitis and increased the expression of mucins." (PMID 41010526, 2025). "This study also showed a significant increase in MUC5AC/Muc5ac expression during colonic inflammation in biopsies from UC patients and DSS-induced mice colitis." (PMID 34638564, 2021). "Given the previous findings on body weight, DAI scores, colon length, and intestinal barrier damage, all of which indicated that APS alleviated DSS-induced colitis in a dose-dependent manner, we selected mice in the APS-H group to detect the expression of MUC2 and MUC5AC." (PMID 41010526, 2025). "Previous studies have shown that in DSS-treated mice, MUC2 and MUC5AC levels were reduced, which has been confirmed by previous research that DSS-treated mice had lower MUC2 and MUC5AC levels, which resulted in spontaneous colitis development." (PMID 37836386, 2023).
pulmonary fibrosis (12 papers, 2013 to 2025). Chronic progressive interstitial lung disorder characterized by the replacement of the lung tissue by connective tissue, leading to progressive dyspnea, respiratory failure, or right heart failure. "Finally, neutrophil elastase, one key effector in the progression of lung fibrosis, increases MUC5AC mRNA levels by enhancing mRNA stability." (PMID 31514468, 2019). "Mechanistically, TP-TR downregulated the TLR4/TGF-β level to alleviate airway inflammation and pulmonary fibrosis, concurrently inhibiting MMP9/12 and MUC5AC/5B expression, thereby delaying lung tissue destruction and reducing mucus production." (PMID 40845001, 2025). "Previous studies have identified genetic variants associated with mucin gene expression (eQTL) that are located within or near MUC5AC (in asthma) and MUC5B (in idiopathic pulmonary fibrosis, IPF)." (PMID 37352370, 2023). "CF mouse models, owing to interspecies differences (e.g., airway mucus is primarily composed of mucin MUC5B rather than human MUC5AC), fail to recapitulate typical human CF phenotypes, such as chronic Pseudomonas aeruginosa infection and progressive pulmonary fibrosis." (PMID 40791795, 2025).
chronic bronchitis (11 papers, 2013 to 2024). A type of chronic obstructive pulmonary disease characterized by chronic inflammation in the bronchial tree that results in edema, mucus production, obstruction, and reduced airflow to and from the lung alveoli. "In our cohort, smoking exposure, chronic bronchitis, and emphysema were associated with high MUC5AC expression but with low MUC5B expression in goblet cells of the large airway mucosa." (PMID 39769414, 2024). "Chronic bronchitis, emphysema, and the progression of chronic airflow limitation during a median follow-up time of 8.4 years were associated with higher MUC5AC and lower MUC5B expression in goblet cells." (PMID 39769414, 2024). "In line with this, in our cohort, high MUC5AC and low MUC5B expression were associated with smoking exposure as well as with unfavorable traits of COPD, such as chronic bronchitis and emphysema." (PMID 39769414, 2024). "Collectively, the current study indicates that high MUC5AC expression and low MUC5B expression in goblet cells in the large airways are associated with cigarette smoke exposure and with chronic bronchitis and emphysema." (PMID 39769414, 2024). "Patients with chronic bronchitis had higher immunohistochemical MUC5AC expression, higher MUC5AC concentration in BW, and lower immunohistochemical MUC5B expression in goblet cells, as compared with patients without chronic bronchitis at baseline." (PMID 39769414, 2024). "The composition of the mucus can also be varied, for example, the mucin MUC5B:MUC5AC ratio is increased in chronic bronchitis sputum." (PMID 37901462, 2023). "In several airway diseases with mucociliary dysfunction, such as chronic bronchitis, the MUC5AC-to -UC5B ratio is increased." (PMID 36675209, 2023). "Similarly, chronic bronchitis, which is recognized as an unfavorable clinical trait of COPD, was associated with lower MUC5B expression, higher MUC5AC expression, and higher MUC5AC concentration in BW." (PMID 39769414, 2024). "Moreover, the sputum MUC5AC and MUC5B concentrations were associated with common genetic variants, and the top locus for MUC5B might influence COPD phenotypes, in particular chronic bronchitis." (PMID 39769414, 2024). "Wood smoke exposure resulted in increased expression of MUC1, MUC5AC, and MUC5B in the chronic bronchitis-like bronchial model." (PMID 38245732, 2024). "In this study, we focused on the effects of the extracts from PG on the concentrations of a few factors possibly involved in pathogenesis of chronic bronchitis (VEGF, TGF-β1, TGF-β2, TGF-β3, MUC5AC, and CRP)." (PMID 33138217, 2020). "In rats with chronic bronchitis induced by MBS concentrations of selected factors VEGF, TGF-β1, TGF-β2, TGF-β3, MUC5AC, and CRP were determined using appropriate ELISA methods." (PMID 33138217, 2020). "It has been proposed that mucus concentration and the absolute concentrations of MUC5AC and MUC5B could be used as biomarkers of chronic bronchitis." (PMID 36675209, 2023).
eosinophilia (11 papers, 2011 to 2025). "Thus, aerosolized OVA stress in neonatally OVA-sensitized mice triggered asthmatic lungs with Gob5/MUC5AC gene upregulation, airway eosinophilia, and structural alterations in association with marked increment of airway resistance to bronchospastic stimuli." (PMID 34207237, 2021). "We first performed a concentration-response experiment with HDM extract with a standard sensitization protocol to determine the amount of HDM extract (6.25 μg), which elicited minimal BHR, eosinophilia, and Ccl11 and Muc5ac mRNA in WT mice." (PMID 27489884, 2016). "It attenuated OVA-induced lung tissue eosinophilia and airway mucus production, mRNA expression of E-selectin, IL-17, IL-33 and Muc5ac in lung tissues, and airway hyperresponsiveness to methacholine." (PMID 21695271, 2011). "In patients with COPD, asthma, and non-CF bronchiectasis, our team recently demonstrated that sputum rheology (elastic modulus G’, viscous modulus G’’, and critical stress σc), was correlated with MUC5AC and MUC5B mucin content and sputum eosinophilia." (PMID 36979719, 2023). "Accordingly, there was increased expression of Muc5ac, pro-Th2 and Th17 cytokine (e.g., Il13, Il33 and Il17a), increased BALF eosinophilia, as well as increased genes involved in epithelial repair responses in the lungs (e.g. Egfr and Tff2)." (PMID 31089182, 2019). "Additionally, nicotine-containing aerosols altered mucin expression (notably MUC5AC) and increased airway eosinophilia, while nicotine-free aerosols did not." (PMID 40559943, 2025).
airway hyperresponsiveness (10 papers, 2018 to 2025). "In inflamed airways, MUC5B contributes to honeycomb-like structures and plays a role in mucociliary transport, whereas MUC5AC is associated with mucus plug formation and airway hyperresponsiveness." (PMID 40869396, 2025). "MUC5AC is the prime mucin of airway epithelia, which often abnormally expresses and is associated with airflow obstruction and airway hyperresponsiveness in patients with COPD." (PMID 33302350, 2020). "At the molecular level, the HDM challenge elevated the expression of major Th2 cytokines (IL-4 and IL-13), IL-17a, and muc5ac, which are key mediators of airway hyperresponsiveness and mucus overproduction." (PMID 39682780, 2024). "Muc5b has physiologic functions, ensuring normal mucus clearance, whereas Muc5ac plays a role in mechanisms of allergen-induced airway hyperresponsiveness, mucous metaplasia, and airway mucus plugging." (PMID 29614747, 2018). "IgG-treated animals exhibited attenuated allergen-induced production of IgE, IL-4, and IL-13, along with impaired OVA-induced goblet cell hyperplasia and Muc5ac expression and suppressed airway hyperresponsiveness, consistent with a shift away from a Th2 response." (PMID 40725026, 2025). "The results demonstrated that intratracheal administration of mASCs could not only reduce airway hyperresponsiveness, inflammatory cell infiltration, and Muc5ac secretion, but also improve airway remodeling." (PMID 30089474, 2018).
gastric tumor (10 papers, 2012 to 2023). "MUC5AC was used as a marker of gastric phenotype in stomach tumors, and its expression was associated with tumor stage." (PMID 28938681, 2017). "Specifically, Kaplan–Meier curves indicated that low mRNA expression of MUC5AC and MUC6 in gastric tumor tissue correlated with worse survival (P ≤ 0.027)." (PMID 37085819, 2023). "SOX2, CDX2, MUC5AC and MUC2 expression were assessed in 201 gastric tumors by immunohistochemistry." (PMID 25300947, 2014). "On the other hand, immunostaining was positive for CK7, CK20, MUC5AC and caudal type homeobox 2 expression in the gastric tumor, but negative in the lung tumor, indicating that each adenocarcinoma was a synchronous double cancer." (PMID 22938085, 2012). "Associated to mucins, too, is the family of trefoil factors, including the gastric tumor suppressors TFF1 and TTF2, which are co-localized with MUC5AC and MUC6, respectively; and TFF3, which is typically not secreted by gastric mucosa but, like MUC2, by goblet cells." (PMID 34227026, 2021).